IL33 (interleukin 33)
Diseases named in the same sentence as IL33 in open-access papers (continued):
Sharing a sentence is not in itself a finding about the gene and the disease.
tumor (continued). "One study has shown that the level of IL-33 secreted in tumor tissues is positively correlated with the infiltration of mast cells, and studies have demonstrated that IL-33 can increase the number of mast cells in tumors through apoptosis." (PMID 39925809, 2025). "We further explored the cooperative action of DAC with the IL-33/ST2 axis in the tumor-immune crosstalk by means of 3D microfluidic chip-based competitive assays." (PMID 40317004, 2025). "Among these, IL-33 and IL-18 play key roles in tumor biology and immunology in different types of cancers, including breast, CRC, and CML." (PMID 40247153, 2025). "A combined model incorporating IL-8, IL-17A, IL-33, and tumor grade accounted for over 70% of IL-17A variability, underscoring their interactive role in CRC biology." (PMID 40725273, 2025). "Eosinophils and basophils similarly respond to IL-33, enhancing type 2 immunity and potentially facilitating fibrosis and tumour progression." (PMID 41284319, 2025). "Intriguingly, a recent study has shown that IL-33 can enhance the anticancer activity of eosinophils by reprogramming tumor cells, suggesting a novel approach for cancer therapy." (PMID 39925809, 2025). "IL-33 affects Tregs, promoting tumor immune escape, and CD8+ T cell-derived IL-33 mediates cytotoxicity within the TME." (PMID 39925809, 2025). "IL-17A and IL-33 levels declined progressively with tumor dedifferentiation and increased invasion depth, indicating immune suppression in advanced stages." (PMID 40725273, 2025). "We find that IL-33-positive cells mainly reside outside of the tumor bulk and are localized both close to the tumor and further away in the ipsilateral hemisphere, and contralateral hemisphere." (PMID 39931535, 2025). "Simultaneously, increased tumour-derived IL-33 was released, indicating enhanced effector function of endogenous CD8+ T cells, which improves CAR T cell antitumour function." (PMID 40361460, 2025). "It showed that epithelial KRAS-dependent stromal IL33 expression affected the pancreatic TME, as the loss of this cytokine increased CD8+ T cell infiltration and activation and, ultimately, reduced tumor growth, making IL33 another therapeutic target option." (PMID 40805153, 2025). "The data suggest that all three interleukins—IL-8, IL-17A, and IL-33—tend to be more elevated in well-differentiated tumors (G1) and decline with increasing tumor grade." (PMID 40725273, 2025). "Analysis of coronal sections across the tumor-bearing brain showed that a majority of IL-33-positive cells (≥80%) also co-express OLIG2, and more than half (around 60%) co-express CNPase while co-labeling with GFAP is seen in 5% of the IL-33-positive cells." (PMID 39931535, 2025). "In the tumor microenvironment (TME), both tumor and stromal cells, such as fibroblasts, epithelial cells and some immune infiltrating cells are source of IL-33." (PMID 40317004, 2025). "IL-33 is a member of the IL-1 family of cytokines that can be involved in different pathways in immune response and tumor biology." (PMID 40943444, 2025). "Overexpression of IL-33 in CAFs correlates with its expression in tumor cells, as per some of these reports." (PMID 40196136, 2025). "When IL-33 is sequestered in the nucleus of tumor cells, it drives reprogramming of TAMs toward tumor-supportive functions, facilitating immune evasion and rapid tumor progression." (PMID 41374974, 2025). "Studies have demonstrated that the injection of IL-33 into melanoma-bearing mice inhibits tumor progression and prolongs survival, while also reducing lung metastasis in mice with breast cancer." (PMID 40877572, 2025). "In tumors, IL-33 plays a dual role, and future anti-tumor strategy research will require targeted studies based on different pathways in different tumors to develop effective treatment strategies." (PMID 39925809, 2025).
tumor (continued). "IL-33 is released from necrotic or stressed stromal and epithelial cells (as an alarmin) and can significantly affects the tumour microenvironment (TME) by modulating both innate and acquired anti-tumour immune responses." (PMID 41284319, 2025). "IL-33 and has gained attention for its contribution to tumor progression, and has also been shown to have both pro- and anti-tumorigenic effects (reviewed by Robbins19) in a context-dependent manner." (PMID 39931535, 2025). "We then generated organoids from clinical EGC (3 cases) and AGC (3 cases) samples to determine the role of IL‐33 in tumor cells." (PMID 40860436, 2025). "Targeting this pathway, a recent study has published a combination of IL-33 and p38 inhibitors, which synergistically inhibit tumor growth and metastasis." (PMID 39925809, 2025). "In particular, IL-33 driven eosinophils are known to promote anti-tumor responses through the production of CD8 T cell-attracting chemokines, release of extracellular vesicles and direct cytotoxicity." (PMID 40317004, 2025). "Schwann cells secrete IL-33, recruiting macrophages into the perineural environment and promoting their M2 tumor-promoting polarization." (PMID 41132793, 2025). "IL-33 enhances eosinophil-mediated tumor cell killing by promoting adhesion and degranulation, which is crucial for their cytotoxic function in the TME." (PMID 40305195, 2025). "In contrast, Venous‐1 cell subsets express the specific endothelial cell genes IL‐33, MADCAM1, SELP, and SELE, which are closely associated with leukocyte adhesion, angiogenesis, and tumor progression." (PMID 40860436, 2025). "Next, we focused on IL-33 in the tumor microenvironment, using xenograft mouse models where GBM cells from 2 different patients were injected into the striatum of immunodeficient mice." (PMID 39931535, 2025). "This suggests that while IL-33 levels are elevated in well-differentiated tumors and decline with decreasing cellular differentiation in some contexts, its overall association with tumor grade may be more complex or require larger cohorts for definitive statistical significance." (PMID 40725273, 2025). "The rationale for armoring with IL-33 arose from studies that found that IL-33 activates intratumoral group 2 innate lymphoid cells (ILC2s) which can contribute to tissue-specific tumor immunity." (PMID 41019052, 2025). "The cytokines IL-33 and IL-13, central players in type 2 immune responses, play significant roles in promoting an immunosuppressive tumor microenvironment that favors cancer progression." (PMID 40761291, 2025). "IL-33, which is secreted not only by epithelial and endothelial cells but also by damaged or necrotic tumor cells, plays a central role in this process by activating ILC2s and reshaping the TME." (PMID 40963622, 2025). "Despite conflicting reports on IL-33’s pro- or anti-tumor effects, its role as a potent TME regulator is clear, influencing tumor phenotype and malignancy via immune cell recruitment." (PMID 39925809, 2025). "IL-33 and IL-25 activation induced ILC2s to secrete IL-5, which recruited eosinophils, thereby promoting prolonged anti-tumor immune activity." (PMID 40497988, 2025). "Antibodies to OLIG2, a marker of oligodendrocytes and oligodendrocyte progenitor cells, also co-label IL-33 positive cells in the tumor microenvironment." (PMID 39931535, 2025). "This provides a new research direction for IL-33 in the treatment of type I immunomodulatory inflammatory diseases and T cell-based tumor immunotherapy." (PMID 39925809, 2025). "Future studies should further explore these downstream signaling pathways to comprehensively elucidate their mechanisms and refine our understanding of the functional role of CAF-derived IL-33 in tumor development." (PMID 41272907, 2025). "In contrast, IL-33 exhibited an inverse expression pattern, suggesting opposing roles of these molecules in tumor vasculature." (PMID 41374934, 2025).
tumor (continued). "Although the function of IL-33 in driving the immune response has been extensively examined, its role in regulating the therapeutic resistance of tumor cells is only beginning to be explored." (PMID 40216748, 2025). "Although we cannot exclude that in vivo DAC induces the expression of the cytokine also in fibroblast and stromal cells, our in vitro experiments suggest that IL-33 is tumor-derived." (PMID 40317004, 2025). "It is possible that increased release of IL-33 contributes to less potent type 2 anti-tumor immunity and diminishes functional anti-tumor immune response." (PMID 40943444, 2025). "This superkine is then linked with IL-33 genes via a T2A self-cleaving peptide and inserted into a retroviral vector alongside the CAR construct (TA99 CAR) targeting tumor-associated antigens." (PMID 41584600, 2025). "Tumoral organoids have been shown to activate MCs via the IL-33/ST2 axis leading to increased release of TNF-α which in turn was responsible for the observed effects on tumoral organoids." (PMID 40372523, 2025). "The IL-33/ILC2 axis plays a multifaceted role in tumor development and progression in different types of cancer." (PMID 40247153, 2025). "Due to the differences in the role of IL‐33 in different tumor types and microenvironments, its clinical use still needs to be carefully evaluated." (PMID 40860436, 2025). "In contrast to previous results, in this study, we showed that IL‐33‐dependent tumor growth and pulmonary metastasis occurred following subcutaneous (ectopic) implantation of sST2‐knockdown cells." (PMID 40751595, 2025). "Due to its ability to tailor the tumor immune microenvironment, IL-33 represents a promising candidate for combinatorial anti-cancer therapies." (PMID 40317004, 2025). "This inhibition can be reversed by PD-1 blockade, which synergizes with IL-33 to expand ILC2s, amplify their Th2 cytokine production, and enhance anti-tumor activity." (PMID 40963622, 2025). "Although we focused on IL-33 expression patterns in blood endothelial cells in human mandibular gingival cancer, a previous study reported upregulated IL-33 expression levels in OSCC tumor tissues, which were further enriched in the metastatic niche." (PMID 41374934, 2025). "By enhancing the production of matrix metalloproteinases and vascular endothelial growth factor (VEGF), IL-33 creates an environment conducive to tumour invasion." (PMID 41284319, 2025). "The growth of extrahepatic biliary duct organoids was stimulated by IL-33 and immunohistochemistry demonstrated that IL-33 was overexpressed in CCA tumor tissue." (PMID 40823086, 2025). "Specifically, recent studies have demonstrated that KLRG1+ ILC2s can acquire anti-tumor functions through IL-10 production and IL-33–mediated activation." (PMID 40497988, 2025). "This inflammation is initiated by tumor-derived signals, including IL-1, IL-6, and IL-33, which activate surrounding stromal and immune cells." (PMID 41374974, 2025). "In endometrial cancer, elevated IL-31 and IL-33 levels correlate with tumor stage, serving as prognostic biomarkers, while IL-11 blockade reduces tumor growth and metastasis in mouse models." (PMID 41029427, 2025). "This suggests that glia-derived IL-33 participates in orchestrating the brain’s anti-tumor response in an ST2-dependent manner." (PMID 39931535, 2025). "This mini-review focuses on the complex and often opposing roles of two key cytokines, IL-33 and IL-38, within the tumour microenvironment and their implications for host immunosurveillance in PCa." (PMID 40607441, 2025). "It has been demonstrated that Th2 cells, which are controlled by cytokines such as IL-25 and IL-33, stimulate tumorigenesis and metastasis, and that pharmacological inhibition successfully prevents tumor growth." (PMID 39996755, 2025).
tumor (continued). "The percentage of IL-33-positive cells in each category was calculated and compared to non-tumor brains." (PMID 39931535, 2025). "In the TME, recruitment and activation of ILCs by IL-33 can enhance anti-tumor immunity or facilitate tumor progression, depending on the context and balance of the immune response." (PMID 40497988, 2025). "Next, we assessed IL-33 immunostaining of a tissue microarray (TMA) with GBM tumor cores (n = 22) and control brain tissues (n = 7)." (PMID 39931535, 2025). "In contrast, when present in the tumor stroma and serum, IL-33 facilitates immune suppression through Tregs and myeloid-derived suppressor cells." (PMID 40149674, 2025). "In 4T1 and CT26 models, IL-33 pathway inhibition combined with anti-PD-L1 significantly suppressed tumour growth, reduced intratumoral Tregs, and extended survival." (PMID 41284319, 2025). "IHC staining of subcutaneous xenografts revealed decreased KRT17 expression in tumor cells in the IL‐33‐knockdown group." (PMID 40860436, 2025). "Nonetheless, our novel findings underscore a significant relationship between Arid1a and IL-33, particularly relevant to the type 2 immunity-dominant tumor microenvironment." (PMID 40761291, 2025). "IL-33 activates the polarization of macrophages and the production of high-affinity IgE receptor-FcεRIα, and FcεRIα mediates TICs and promotes tumor invasion and drug resistance." (PMID 39925809, 2025). "This cascade leads to increased IL-33 production, a cytokine known to play a significant role in anti-tumor immunity." (PMID 41163402, 2025). "Meanwhile, IL‐33+ endothelial cells can up‐regulate the expression of KRT17 in EGC organoids to promote tumor growth." (PMID 40860436, 2025). "Within the TME, IL-33 is produced by a variety of cell types, including stromal fibroblasts, endothelial cells, and occasionally tumour cells themselves." (PMID 41284319, 2025). "Among these, IL-33 is a key player in cancer biology and is involved in various aspects of tumor development by modulating the immune response." (PMID 40247153, 2025). "Several studies have shown that expression of IL-33 correlates with tumor aggressiveness and poor prognosis of cancer patients." (PMID 40943444, 2025). "First, IL33 has a strong immune effect in tumor response, but in some cases, IL33 can also inhibit immune escape, which makes IL33 a strategy for targeted therapy complicated." (PMID 39911848, 2025). "In several experimental and clinical studies, IL-33 has been shown to contribute to CRC progression by promoting tumor growth, angiogenesis, immune suppression, and metastasis." (PMID 40725273, 2025). "Previous research has identified regulatory T cells and myeloid-derived suppressor cells as primary targets of IL-33, reinforcing the potential benefit of tropisetron-mediated IL-33 suppression in reversing the immunosuppressive tumor microenvironment in PDAC." (PMID 40647388, 2025). "Current studies suggest that some signals, such as IFN-γ and IL-33, promote intratumoral accumulation of eosinophils and polarize them towards anti-tumor functions." (PMID 40050933, 2025). "Nevertheless, it is worth noting that intratumoral administration of IL-33 was as efficient as systemic delivery IL-33 in inducing tumor-infiltrating eosinophils and CD8 T cells and in delaying tumor growth." (PMID 40317004, 2025). "Reduced IL-33 expression in tumor cells decreases immunogenicity, while stromal IL-33 promotes progression and metastasis by mobilizing MDSCs and Tregs." (PMID 39925809, 2025). "IL-33 can also increase immune responses to cancer cells reducing Treg expansion or enhancing tumor-infiltrating ILC2s." (PMID 40305195, 2025). "Upon release by both tumor and stromal cells, IL-33 activates ILC2s through its receptor, ST2, leading to the production of cytokines such as IL-5 and IL-13." (PMID 40247153, 2025).
tumor (continued). "As an alarmin released from necrotic cells, IL-33 modulates antitumor immune responses and influences tumour biology, including angiogenesis and proliferation." (PMID 41284319, 2025). "In this study, we demonstrated that IL-33 within the tumor microenvironment (TME), primarily secreted by cancer-associated fibroblasts (CAFs), can enhance DNA damage-resistance in tumor cells by activating the MAPK/NHEJ pathway." (PMID 40216748, 2025). "Under certain circumstances, IL-33 promotes tumour growth and immune evasion, while in others it can enhance antitumor immunity." (PMID 41284319, 2025). "Collectively, these results indicate the involvement of the IL‐33/ST2L axis in promoting tumor growth and the antitumor effects of sST2." (PMID 40751595, 2025). "While the PD-1/PD-L1 axis is a well-established target in immune checkpoint therapy, the IL-33/ST2 signalling pathway has emerged as a novel potential modulator of anti-tumour immunity, with both pro- and anti-tumorigenic roles." (PMID 41284319, 2025). "After treating immunodeficient mice with an anti-IL-33 antibody, cancer growth, M2 macrophage polarisation and the number of Tregs at the tumour site were reduced." (PMID 38662248, 2024). "Since only DCs among APCs have the potential for enhanced immunogenicity by IL-33, IL-33 has emerged as a promising candidate for successful DC-based tumor immunotherapy." (PMID 38825642, 2024). "This review delves into the intricate landscape of IL-33 effects within the tumor microenvironment, highlighting its pivotal role in orchestrating immune responses against cancer." (PMID 38881897, 2024). "Consistently, IL-33−/− tumor-bearing mice had lower frequencies of tumor-infiltrating CD4+ T cells and CD8+ T cells, while no consistent alterations were observed in the overall populations of CD4+ T cells and CD8+ T cells." (PMID 38430390, 2024). "Next, we analyzed the most potent inducer IL-33 protein in tumor tissues, we found that IL-33 is widely expressed in tumor tissues." (PMID 38430390, 2024). "Conversely, treatment with recombinant IL-33 and anti-PD-1 decreased tumor burden, with IL-33 stimulation enhancing the sensitivity of ILC2s to anti-PD-1 therapy." (PMID 39574565, 2024). "IL33 exhibited tumor restriction in PDAC models by stimulating or restoring anti-tumor activity of CD8+ T and NK cells and was shown to act as an immunoadjuvant to enhance antigen-specific tumor immunity." (PMID 38942797, 2024). "At low E:T ratios such as 1:1, IL-33 readily induced substantial apoptosis of SNU601 cells (P = 0.0006), suggesting that IL-33 was essential for PBMC-mediated killing of tumor cells." (PMID 38238529, 2024). "Based on the effect of IL-33 or IL-33-induced FCGR3+CD103+ cDC1s on tumor therapy in mice, we propose several approaches to translate the antitumor effect of IL-33 observed in mice to humans." (PMID 38825642, 2024). "Within the tumour microenvironment, epithelial cells, dendritic cells, macrophages, myeloid-derived suppressor cells (MDSCs), fibroblasts and cancer cells produce IL-33." (PMID 38662248, 2024). "In contrast, the upregulation of IL-33 during the transition from acute to chronic inflammation initiates the development of a tumor-promoting immune environment." (PMID 38816352, 2024). "The degree of bloody ascites was more obvious in the vehicle group compared with the IL-33 treatment group, indicating that IL-33 reduced the tumor load in the abdominal cavity of mice." (PMID 38238529, 2024). "Our work also documented that the presence of ILC2s significantly inhibits tumour formation in wild-type chimeric mice bearing tumours expressing IL-33 when compared to RORα-/- chimeras, which lack ILC2s." (PMID 38172434, 2024). "Understanding the intricate interplay between the immune response, cytokine treatments like IL-33, and tumor progression is crucial for developing targeted and effective immunotherapies." (PMID 38524132, 2024).